FUBP1 (far upstream element binding protein 1)
Diseases named in the same sentence as FUBP1 in open-access papers (continued):
Sharing a sentence is not in itself a finding about the gene and the disease.
gastric cancer (9 papers, 2019 to 2025). A primary or metastatic malignant neoplasm involving the stomach. "Here, we first depleted FUBP1 expression in gastric cancer cell lines using shRNAs and demonstrated that knockdown of FUBP1 markedly suppressed the gene expression of USP29 in all three cell lines." (PMID 38233848, 2024). "Furthermore, pentadecanoic acid derived from A. muciniphila inhibits glycolysis by antagonizing the activity of far upstream element binding protein 1 (FUBP1), thereby enhancing the sensitivity of gastric cancer to oxaliplatin." (PMID 40028328, 2025). "However, whether FUBP1 is a bona fide regulator of USP29 in gastric cancers remains unclear." (PMID 38233848, 2024). "Activation of USP29 by FUBP1 promotes the stability of AURKB and its oncogenic functions in gastric cancer." (PMID 39605891, 2024). "In terms of mechanism, USP29 is transcriptionally activated by FUBP1, and the deregulated USP29 interacts with and stabilizes AURKB, forming a FUBP1-USP29-AURKB axis that enables tumor cell proliferation and survival in gastric cancers." (PMID 38233848, 2024). "Importantly, there was a significant correlation between FUBP1 and USP29 protein expression levels (R = 0.5074, p = 0.0019) in 35 gastric cancer samples, suggesting that FUBP1 may regulate USP29 expression in vivo." (PMID 38233848, 2024). "The silencing of FUBP1 could advance chemosensitivity to adriamycin in gastric cancer, and the expression of this protein in B-cell non-Hodgkin lymphoma is associated with cell adhesion-mediated drug resistance." (PMID 33791202, 2021). "Similarly, through modulating cyclin J (CCNJ) and far upstream element-binding protein 1 (FUBP1), exogenous expression of miR-16 could reverse the resistance to trastuzumab and lapatinib in HER2 positive gastric cancer cells." (PMID 32192494, 2020).
liver cancer (8 papers, 2019 to 2025). An epithelial or non-epithelial malignant neoplasm that arises from the liver. "At the end of the 2010s, FUBP1 represented one of the fifty types of specific factors already reported to regulate c-myc transcription, whose overexpression was associated with the regulation of proliferation and migration in liver cancer cells." (PMID 34445271, 2021). "It was found that FUBP1 is overexpressed in both fully differentiated and poorly differentiated liver cancer cells." (PMID 33954195, 2021). "Gene set enrichment analysis (GSEA) showed that upon the high and low expression of FUBP1 in liver cancer, downstream genes were evidently relevant to the apoptosis pathway." (PMID 32555178, 2020). "In addition, a study on digestive tract tumors showed that FUBP1 directly or indirectly induced tumor cell proliferation in the liver cancer cell cycle." (PMID 35546072, 2022). "FUBP1 and FUBP2 have been shown to promote proliferation and invasion, while another study observed that these proteins are highly expressed in less differentiated liver cancer tissues." (PMID 39866240, 2025).
pancreatic cancer (8 papers, 2020 to 2026). "In addition, univariate analysis with the Cox proportional hazards model identified both high FUBP1 level (HR = 1.771, p = 0.044) and tumor grade (HR = 2.090, p = 0.013) as statistically significant risk factors influencing the clinical survival of pancreatic cancer patients." (PMID 38443680, 2024). "In pancreatic cancer (PC), tiRNA-Val-CAC-2 enhances pancreatic cancer cell migration and invasion by binding to the RNA-binding protein far upstream element-binding protein 1 (FUBP1), increasing its stability, and activating c-MYC transcription." (PMID 41550494, 2026). "tiRNA-Val-CAC-2 is significantly upregulated in metastatic pancreatic cancer lesions, promoting metastasis by enhancing FUBP1 stability and upregulating c-MYC transcription." (PMID 40153423, 2025). "To evaluate the potential impact of FUBP1 on c-MYC transcription in pancreatic cancer cells, we performed ChIP assays using specific antibody against FUBP1." (PMID 38443680, 2024). "To investigate the potential influence of tiRNA-Val-CAC-2 on pancreatic cancer metastasis through FUBP1 in vivo, we conducted rescue animal experiments." (PMID 38443680, 2024). "Previous studies have reported that FUBP1 is capable of promoting epithelial-mesenchymal transition of pancreatic cancer cells through the TGF-β/Smad pathway." (PMID 38443680, 2024). "We further observed a reduction in c-MYC expression levels in FUBP1-knockdown pancreatic cancer cells." (PMID 38443680, 2024). "High levels of circulating anti-FUBP1 aAb are a good prognostic marker of tail-body pancreatic cancer." (PMID 37910256, 2023). "FUBP1 is a target of irofulven, a novel anti-cancer compound whose anti-tumor activity in an advanced pancreatic cancer patient was documented." (PMID 35626021, 2022). "Further mechanistic investigations revealed that tiRNA-Val-CAC-2 could interact with RNA-binding protein FUBP1, leading to the increase of FUBP1 protein stability, which further promotes pancreatic cancer metastasis by c-MYC transcription." (PMID 38443680, 2024). "Taken together, these results suggest that FUBP1 may play a critical role in the regulation on c-MYC transcription in pancreatic cancer probably through interaction with FUSE motif." (PMID 38443680, 2024). "Of note, rescue experiments confirmed that tiRNA-Val-CAC-2 could influence pancreatic cancer metastasis via FUBP1-mediated c-MYC transcription." (PMID 38443680, 2024). "Nevertheless, the precise mechanisms of FUBP1 in pancreatic cancer remain elusive." (PMID 38443680, 2024). "As such, it is hypothesized that tiRNA-Val-CAC-2 disrupts the interaction between FUBP1 and related ubiquitin ligases in pancreatic cancer." (PMID 38443680, 2024). "Furthermore, we investigated the association between tiRNA, FUBP1, and c-MYC using tumor samples obtained from 12 pancreatic cancer patients." (PMID 38443680, 2024). "Taken together, our findings uncovered a novel mechanism in which a tsRNA, tiRNA-Val-CAC-2, regulates pancreatic cancer metastasis, indicating that tiRNA-Val-CAC-2 and FUBP1 could serve as promising therapeutic targets for pancreatic cancer." (PMID 38443680, 2024). "Previously, we found that the RB–p65 axis 10, FUBP1–Myc axis 20, HAT1–BRD4 axis 21 or HDAC3 22 regulated PD‐L1 expression in pancreatic cancer." (PMID 31898405, 2020). "Since tiRNA-Val-CAC-2 is capable of promoting FUBP1-mediated c-MYC transcription in pancreatic cancer cells, we further hypothesized that tiRNA-Val-CAC-2 may promote metastasis in pancreatic cancer through FUBP1 to active c-MYC transcription." (PMID 38443680, 2024).
osteosarcoma (6 papers, 2021 to 2023). A usually aggressive malignant bone-forming mesenchymal neoplasm, predominantly affecting adolescents and young adults. "In our current study, we observed that high expression of FUBP1 was associated with poor osteosarcoma patient survival." (PMID 37180822, 2023). "siRNA knockdown of FUBP1 showed a strikingly decreased IC50 value for lobaplatin in FUBP1-silenced cells, which verified the role of FUBP1 in the drug susceptibility of osteosarcoma and the potential therapeutic value for increasing the sensitivity to lobaplatin." (PMID 33791202, 2021). "The protein levels of cleaved caspase 3 and cleaved poly (ADP‐ribose) polymerase (PARP) were significantly decreased in FUBP1‐overexpressing osteosarcoma cells." (PMID 37180822, 2023). "Overexpression of FUBP1 conferred lobaplatin resistance in osteosarcoma, whereas inhibition of FUBP1 using either siRNA or lentivirus‐mediated shRNA sensitized osteosarcoma cells to lobaplatin both in vitro and in vivo." (PMID 37180822, 2023). "We found that the expression level of FUBP1 in the clinical osteosarcoma samples was positively correlated with the expression level of PTGES and CYP2C19 (p = 0.002, and p = 0.005)." (PMID 37180822, 2023). "We also found that the upregulation of PTGES significantly decreased the sensitivity of osteosarcoma cells to lobaplatin due to interference with FUBP1." (PMID 37180822, 2023). "We found that overexpression of FUBP1 confers lobaplatin resistance, whereas the inhibition of FUBP1 sensitizes osteosarcoma cells to lobaplatin‐induced cytotoxicity both in vivo and in vitro." (PMID 37180822, 2023). "High expression of FUBP1 was correlated with a more aggressive phenotype and a poor prognosis in osteosarcoma patients." (PMID 37180822, 2023). "The proportion of apoptotic cells in FUBP1‐overexpressing osteosarcoma cells treated with lobaplatin was markedly reduced, whereas this proportion was increased in FUBP1‐silenced osteosarcoma cells." (PMID 37180822, 2023). "Our findings provide evidence that FUBP1 plays a critical role in the process of lobaplatin resistance in human osteosarcoma through the transcriptional regulation of PTGES and activation of AA metabolism." (PMID 37180822, 2023). "Our investigation provides evidence that FUBP1 is a potential therapeutic target for osteosarcoma patients." (PMID 37180822, 2023). "Western blotting revealed that the expression level of cleaved PARP decreased in the cotransfected osteosarcoma cells compared with the FUBP1‐silenced cells when 20 μg/mL lobaplatin was administered to the tumor cells for 24 h." (PMID 37180822, 2023). "In osteosarcoma, we found that FUBP1 was upregulated and that overexpression of FUBP1 promoted drug resistance to lobaplatin." (PMID 37180822, 2023). "We compared the expression of FUBP1 in osteosarcoma cell lines, an osteoblast cell line, osteosarcoma tumor tissues, and nontumorous bone tissues at both the protein and mRNA levels." (PMID 37180822, 2023). "FUBP1 was clearly upregulated in the six different osteosarcoma cell lines and six osteosarcoma tumor tissues compared to the osteoblast cell line human fetal osteoblasts (hFOB) 1.19 and normal bone tissues." (PMID 37180822, 2023). "In this investigation, we presented the first demonstration that FUBP1 overexpression confers lobaplatin resistance, whereas FUBP1 knockdown increases lobaplatin sensitivity in human osteosarcoma both in vitro and in vivo." (PMID 37180822, 2023). "Immunohistochemistry (IHC) analysis showed that FUBP1 was markedly upregulated in osteosarcoma tissues compared with normal bone tissues." (PMID 37180822, 2023). "We then detected the metabolites of AA (PGE2 and LTB4), which showed increased expression in FUBP1‐overexpressing osteosarcoma cells." (PMID 37180822, 2023). "Our study indicated the potential therapeutic value of FUBP1 and AA metabolism for increasing the sensitivity to lobaplatin in patients with osteosarcoma." (PMID 37180822, 2023).
osteosarcoma (continued). "The necessity of PTGES activation to allow FUBP1 to enhance resistance to chemotherapy in osteosarcoma cells was further investigated." (PMID 37180822, 2023). "The expression of far upstream element‐binding protein 1 (FUBP1) was found to be markedly elevated in osteosarcoma cell lines and clinical specimens compared with osteoblast cells and normal bone specimens." (PMID 37180822, 2023). "High expression of far upstream element‐binding protein 1 (FUBP1) on tumor cells promotes lobaplatin chemoresistance in osteosarcoma cells." (PMID 37180822, 2023). "PTGES was dramatically elevated in FUBP1‐overexpressing cells but downregulated in FUBP1‐silenced osteosarcoma cells." (PMID 37180822, 2023). "Our team has focused on the multifunctional FUBP1 protein and has reported on the links between FUBP1 and chemoresistance in human osteosarcoma cells." (PMID 35274005, 2022). "The existing body of research suggest that FUBP1 protein level is increased in human osteosarcoma cell line." (PMID 35546072, 2022). "Combined with the proteomics and bioinformatics results, as well as the immunohistochemistry staining in clinical specimens, we can conclude that FUBP1 is a special protein that confers lobaplatin resistance in osteosarcoma cells." (PMID 33791202, 2021). "Furthermore, FUBP1 was mainly localized in the nuclei of osteosarcoma cells according to the results of the immunofluorescence (IF) assay and the fluorescence in situ hybridization (FISH) assay." (PMID 37180822, 2023). "FUBP1 played a similar role in SOSP‐9607 osteosarcoma cells." (PMID 37180822, 2023). "Understanding the molecular mechanisms of FUBP1 in osteosarcoma progression and chemoresistance may establish FUBP1 and AA metabolism as potential therapeutic targets for the clinical treatment of osteosarcoma." (PMID 37180822, 2023). "Taken together, our results present a novel mechanism of AA pathway activation in osteosarcoma and indicate that targeting FUBP1 might be a novel therapeutic strategy for osteosarcoma patients with lobaplatin resistance." (PMID 37180822, 2023). "Moreover, FUBP1 overexpression dramatically reduced osteosarcoma sensitivity to lobaplatin both in vitro and in vivo, whereas silencing FUBP1 enhanced osteosarcoma sensitivity." (PMID 37180822, 2023). "Moreover, PGE2 inhibition enhances the sensitivity of osteosarcoma cells induced by FUBP1 interference." (PMID 37180822, 2023). "Our previous research found that FUBP1 could decrease the sensitivity of osteosarcoma cells to lobaplatin." (PMID 37180822, 2023). "Moreover, RNA‐seq showed the enrichment of the AA pathway when the sensitivity of osteosarcoma cells to lobaplatin was elevated by FUBP1 knockdown." (PMID 37180822, 2023). "In our previous study, we found that a high level of FUBP1 could confer lobaplatin resistance in osteosarcoma cell lines, which resulted in poor outcomes." (PMID 35274005, 2022). "In the present study, we found that FUBP1 transcriptionally promotes the expression of PTGES and sustains the activation of the AA pathway in lobaplatin‐treatment osteosarcoma cells." (PMID 37180822, 2023). "The average viability of osteosarcoma cells transfected with both FUBP1 siRNA and the PTGES‐overexpression plasmid was markedly higher than that of cells transfected with only FUBP1 siRNA." (PMID 37180822, 2023). "FUBP1 binds to and promotes PTGES promoter activity and sustains the AA metabolism pathway in osteosarcoma cells." (PMID 37180822, 2023). "siRNAs were synthesized to separately silence the three genes, G3BP1, FUBP1, and FXR1, and the sensitivity of osteosarcoma cells to lobaplatin were detected." (PMID 33791202, 2021). "Moreover, we blocked AA metabolic pathway using a selective PTGES inhibitor CAY10526 in FUBP1‐overexpressing osteosarcoma cells and stimulated it using an EP2 receptor agonist Evatanepag in FUBP1‐silenced osteosarcoma cells." (PMID 37180822, 2023).
osteosarcoma (continued). "The significant increases in IC50 values in FUBP1‐overexpressing osteosarcoma cells and decreases in IC50 values in FUBP1‐silenced cells versus control cells suggest that FUBP1 enhances the resistance of osteosarcoma cells to lobaplatin in vitro." (PMID 37180822, 2023). "Targeting FUBP1, its downstream target PTGES and the AA metabolic pathway may be promising strategies for sensitizing chemoresistant osteosarcoma cells to lobaplatin." (PMID 37180822, 2023). "The colony formation assay showed that the colony formation efficiency of FUBP1‐overexpressing osteosarcoma cells (MG63 and SOSP‐9607) treated with lobaplatin increased, whereas that of FUBP1‐silenced cells declined sharply compared with that of the control cells (p < 0.05)." (PMID 37180822, 2023). "The clinical relevance of FUBP1 expression in terms of the activation of PTGES and CYP2C19 (a key CYP epoxygenase enzyme in AA metabolism) was further investigated in a group of human osteosarcoma clinical specimens using IHC analysis." (PMID 37180822, 2023). "Interestingly, three proteins, KHDRBS1, FUBP1, and HNRNPA2B1, are involved in either RNA processing or RNA modification, highlighting the potential role of RNA regulation in osteosarcoma pathogenesis." (PMID 37681913, 2023).
bladder cancer (5 papers, 2019 to 2022). "Our previous study has demonstrated that CRT affects integrin activity through FUBP-1-FUT-1-dependent fucosylation in J82 bladder cancer cells." (PMID 35327448, 2022). "Our previous study in bladder cancer has demonstrated that CRT affects β1-integrin activity through FUBP-1-FUT-1-dependent fucosylation, rather than directly affecting the expression of β1-integrin itself." (PMID 35327448, 2022). "Interestingly, we previously showed that the overexpression of CRT enhanced the expression of RNA binding protein FUBP1, which binds to ARE in 3’ UTR of FUT1 mRNA, and therefore stabilized FUT1 mRNA in J82 bladder cancer cells to promote tumor formation and metastasis." (PMID 31725767, 2019). "However, other studies have reported that the FUBP1-MYC axis might not be ubiquitous since MYC expression is not altered by FUBP1 silencing in different cell types, such as normal fibroblasts, prostate and bladder cancer." (PMID 32481602, 2020). "Our previous study demonstrated that in J82 bladder cancer cells, CRT affects integrin activity through FUBP-1-FUT-1-dependent fucosylation, rather than directly affecting the expression of β1-integrin itself." (PMID 35327448, 2022). "In our previous study on bladder cancer, we showed that CRT was not part of the ARE binding protein complex and that it indirectly stabilized FUT1 mRNA degradation through activating the ARE binding protein FUBP1." (PMID 31725767, 2019).
cervical cancer (5 papers, 2020 to 2023). A primary or metastatic malignant neoplasm involving the cervix. "In the present study, we found that FUBP1 mRNA and protein expressions were markedly upregulated and closely linked with poor prognosis in cervical cancer." (PMID 33987449, 2021). "Transportin-1 (TNPO1)-induced nuclear import of FUBP1 (Far upstream element binding protein 1) led to tumor immune evasion via upregulation of NRP1 in cervical cancer." (PMID 37704909, 2023). "FUBP1, primarily located in the nucleus, was prevented to be imported into the nucleus due to caspase-3/7 cleavage during the breast and cervical cancer cells apoptosis." (PMID 32555178, 2020). "The genetic overexpression of FUBP1 was demonstrated in a multitude of cancers by comparing pan-cancer gene expression, such as cervical cancer (CC), which indicates that FUBP1 may act as an oncogene." (PMID 33987449, 2021). "Additionally, nuclear import of FUBP1 could contribute to tumor immune evasion in cervical cancer." (PMID 37180822, 2023). "FUBP1 expression has not been previously investigated in cervical cancer, but its high expression and enhanced interaction with Kpnβ1 in the cancer cells shown in our study warrants further investigation." (PMID 36418423, 2022).
lung adenocarcinoma (5 papers, 2020 to 2024). A carcinoma that arises from the lung and is characterized by the presence of malignant glandular epithelial cells. "There were 6 genes with a causal relationship to lung adenocarcinoma, including FUBP1, CTD-2012J19.3, CTD-2012J19.1, DCBLD1, NRG1 and SECISBP2L." (PMID 38834983, 2024). "Enhanced phosphorylation of FUBP1 at the S120 site has been observed in clear cell RCC, lung adenocarcinoma, and pediatric brain cancer specimens from African-American and Asian individuals." (PMID 35274005, 2022). "For example, METTL3 increased m6A modification of PCAT6, resulting in PCAT6 upregulation in an IGF2BP2-dependent manner; LCAT3 stability was significantly increased in a METTL3-dependent manner in lung adenocarcinomas, thereby activating MYC transcription via FUBP1." (PMID 35037556, 2022).
nasopharyngeal carcinoma (5 papers, 2015 to 2021). A carcinoma arising from the nasopharyngeal epithelium. "RARS1 fusion with MAD1L1 has been reported to stimulate the FUBP1/c-Myc signaling pathway, inducing tumorigenesis in nasopharyngeal carcinoma." (PMID 35047511, 2021).